CD38 (CD38 molecule)
Diseases named in the same sentence as CD38 in open-access papers (continued):
Sharing a sentence is not in itself a finding about the gene and the disease.
tumor (continued). "In contrast, CD38, whose expression on myeloid cells predicts favourable prognosis hence its anti-tumoural activity in HCC25 and proinflammatory cytokine TNF, were both reduced in S2 and S3 tumours." (PMID 35301339, 2022). "Here, CD24+CD38+ Bregs promote tumour progression through a mechanism involving CD40 and CD40L interactions with cancer cells that subsequently leads to the secretion of IL-10 and TGFβ that sustain tumour proliferation." (PMID 35350071, 2022). "In our study, 89Zr‐labeled dara showed a high tumor uptake at around 20 %ID g−1 and low uptake in other nontarget organs for CD38‐positive models, providing excellent tumor contrast." (PMID 34026426, 2021). "Other studies have demonstrated that CD38 has a role in tumor growth that is independent of the expression of CD38 on immune cells, and is rather due to its expression on tumor cells." (PMID 33467713, 2021). "These TLSs were stained with CD38, CD138, and CD79a to distinguish GCs (which are CD20− but co-express CD38, CD138, and cytosolic CD79a) from naïve and memory B cells (which are CD38−CD138− but express membranous CD79a) and CD138+ tumor or stromal cells." (PMID 34553849, 2021). "Furthermore, activated CD38+ and CD69+ tumor infiltrating T lymphocytes were enriched in TLSHi tumors, implicating TLS to be the site of T cell priming and activation." (PMID 34267760, 2021). "Mechanistically, the knockout of CD38 decreased both CAF numbers and tumor growth." (PMID 34211854, 2021). "Almost all tumor cells were lysed in 48 h with an E:T ratio of 4:1, whereas most of the K562 cells survived, indicating that the cytotoxic function of the CAR‐T cells is CD38‐specific." (PMID 33747727, 2021). "We also tested a combination of anti-CD38, L82-pulsed DC vaccine with CpG, and anti-PD-1 mAb but this did not result in any enhancement of the anti-tumor activity of the treatment." (PMID 34771674, 2021). "To determine the antitumor ability of CD38 CAR-T cells in vitro, we selected different kinds of CD38-positive cells and used CD38-negative tumor cells as a control." (PMID 34513682, 2021). "Additionally, other factors affect anti-tumor immunity through the TME, such as CD38 and the exhausted T cell marker programmed death-1 receptor (PD-1)." (PMID 33747957, 2021). "In different experimental studies, we found that CD38 CAR-T cells have an efficient killing effect on CD38-positive tumor cells but not CD38-negative tumor cells." (PMID 34513682, 2021). "These genes were defined as the tumor reactive signature (TRS), including co-inhibitory receptors (CTLA4, PDCD1, TIGIT and HAVCR2), reactive markers (CD38 and ENTPD1), effector molecules (NKG7 and PRF1), tumor necrosis factor TNFRSF9 and critical exhaustion-related regulator TOX." (PMID 34804045, 2021). "To determine the cytotoxicity of CD38 CAR-T cells on tumor cells, we established an in vitro tumor killing experiment in which CAR-T cells were incubated with different types of CD38-positive tumor cells at different E:T ratios." (PMID 34513682, 2021). "Of note is that, despite the fact that RP02 has a weaker binding affinity to purified CD38, the RP02 CAR‐T cells were more potent than RP03 and 028 CAR‐T cells in terms of cytotoxicity for all tumor cell lines tested, including Daudi, RPMI8226, Raji, and THP cells." (PMID 33747727, 2021). "Tumor slides were immunohistochemically stained for CD3, CD8, CD4, CD20, CD38 and FoxP3." (PMID 33006650, 2021). "Treatment with lenalidomide, dexamethasone and carfilzomib showed a tumor weight reduction of 90% versus non-treated tumors, whereas treatment with the anti-CD38 antibody daratumumab showed a reduction of 46%." (PMID 33988237, 2021). "T cells with reduced surface expression of the NADase CD38 exhibited intrinsically higher NAD+, enhanced oxidative phosphorylation, higher glutaminolysis and altered mitochondrial dynamics that vastly improved tumor control." (PMID 34987512, 2021).
tumor (continued). "Moreover, improved anti-tumor activity was observed particularly upon pre-treatment of AML cells with all-trans retinoic acid, which promoted upregulation of CD38 on malignant cells and hence increased sensitivity toward CD38-CAR-NK treatment." (PMID 34203935, 2021). "Exogenously administration of 8-Br-cADPR was found to induce a significantly decrease of the cytoplasmic calcium in CD38 WT and OE tumor cells but not in CD38 KO and MU cells." (PMID 34226519, 2021). "Isatuximab is an IgG1 monoclonal antibody that induces apoptosis of tumor cells and ADCC; it binds to a specific discontinuous epitope containing amino acids located opposite to the catalytic site of CD38, thus almost completely inhibiting cyclase activity in a dose-dependent manner." (PMID 33727923, 2021). "Increased CD38 activity could result in a low level of intracellular NAD+ and inhibit tumor cell growth, inducing apoptosis." (PMID 34760709, 2021). "But it is controversial about the role of tumor expressed CD38 and its enzymatic activity in the non-hematogenic tumor environment." (PMID 34226519, 2021). "But we did not observe any significant changes of proliferation and migration in tumor cells after treated with NAD+ precursor NMN or ADO, indicated that CD38 might regulate tumor cell proliferation and migration independent on ADO and NAD+." (PMID 34226519, 2021). "Since CD38 could consume NAD+, NAD+ would be elevated by CD38 knock-out and then might stimulate SIRT1 and PARP1 to induce T cell differentiation into Th1 subsets for enhancing the anti-tumor effects." (PMID 34226519, 2021). "CD38 CAR-T cells could be activated effectively after stimulation with CD38-positive tumor cells and secrete cytokines such as IFN-γ and TNF-α to promote tumor cell apoptosis in in vitro experiments." (PMID 34513682, 2021). "Similarly, CD38 inhibitors via anti-CD38 antibodies, NAD analogs, flavonoids, or others, have shown promise in tumor immunity, aging, and metabolic diseases." (PMID 34367184, 2021). "The results showed that CD38 CAR-T cells had a robust killing effect on CD38-positive tumor cells but no specific killing effect on CD38-negative K562-hBCMA cells." (PMID 34513682, 2021). "ISA has been shown to exert both a potent pro-apoptotic effect, regardless of the presence of cross-linking agents, and robust ADCC (the most prevalent effector mechanism for the elimination of tumor plasma), CDC and ADCP against CD38+ malignant subpopulations." (PMID 32531894, 2020). "Mice bearing subcutaneous MM tumours were imaged using 64Copper-labelled anti-CD38 mAbs with and without a dose of unlabelled mAbs." (PMID 32512883, 2020). "Furthermore, Daratumumab effectively targets CD38 expressing myeloid-derived suppressor cells (MDSC) and regulatory T cells, which are known contributors to the formation of an immunosuppressive tumor microenvironment, thus promoting immune escape." (PMID 32225002, 2020). "In addition, many of the current popular target antigens, such as CD38 and SLAMF7 (also known as CS1 or CD319), are also found in other normal tissues, thus leading to unwanted off-tumor toxicities." (PMID 32943087, 2020). "However, S3I-1757 embedded in nanoparticles that had been conjugated with monoclonal antibodies against CD38 (denoted as CD38-S3I-NP) was demonstrated to have some increased efficacy in suppressing P-Y-STAT3 and tumor growth in xenograft models of MM." (PMID 31963765, 2020). "Although it might be beneficial to keep continuous pressure on immune-suppressive subsets to improve the anti-tumor activity of T−cells, we know that CDC, ADCP and ADCC are more efficient, with higher CD38 expression." (PMID 32331242, 2020). "This suggests that daratumumab-mediated CDC is, most likely, not the main driver for the enhanced anti-tumor activity when anti-CD38 and anti-PD-1 antibodies are combined." (PMID 33321969, 2020).
tumor (continued). "Tumor specific CD8 T cells with plastic and fixed exhaustion programs can be distinguished phenotypically depending on the expression of CD101 and CD38 (high in terminally exhausted CD8 T cells) and the transcription factor TCF-1 (low in terminally exhausted CD8 T cells)." (PMID 32391270, 2020). "The results show that CD38-specific Nb-CAR-NKs effectively lyse CD38-expressing tumor cells but not the respective CD38ko daughter cell line." (PMID 32013131, 2020). "Tumor cell uptake of CD38-targeted nanoparticles increased over nontargeted nanoparticles, with increasing uptake of nanoparticles formulated with 0.1–0.5% peptide density, with a large drop occurring between 0.5 and 1% peptide density." (PMID 33138841, 2020). "Therefore, the affinity of the scFv antibody used to develop CD38 CAR T-cell product, needs to be accurately optimized to avoid on-target, off-tumor side effects." (PMID 32582204, 2020). "CD38-targeted nanoparticles displayed significantly increased tumor cell uptake over both nontargeted nanoparticles and the free drug." (PMID 33138841, 2020). "In vivo experiments showed that AMG 424, an anti-CD38/CD3 XmAb T cell-recruiting antibody, promoted tumor cell killing by T cells without causing excessive release of cytokines even if MM cells expressed low CD38." (PMID 33168044, 2020). "The first study was reported in early 2018, in which anti-CD38 conjugated NP carrying bortezomib exhibited a 2 to 3-fold increase in cell uptake by MM cells and a ~50% greater reduction of MM tumor growth compared to non-targeted NP." (PMID 30791634, 2019). "In HGBL, LMO2 was found in moderate intensity in the nucleus, CD38 was not expressed or was weakly expressed in the tumor cells, and c-Myc was detected in some tumor cell nuclei." (PMID 31484540, 2019). "CD38 and CD157 glycoproteins, which are expressed on tumor cells and immune infiltrates, serve a pertinent role in the promotion of tumor progression across multiple kinds of cancer, but may also represent a therapeutic solution." (PMID 31861847, 2019). "Indeed, in tumor-bearing mice, combination of anti-CD38 antibody and anti-PDL-1 antibody suppressed tumor growth and dissemination more than either antibody alone." (PMID 31694167, 2019). "Expression of CD38 on tumor cells was indicated to serve as a negative prognostic marker implying disease severity and poor survival." (PMID 31649684, 2019). "Thus, infiltration of CD38-expressing immune cells during infection, aging, or tumorigenesis has the potential to: alter NAD+ homeostasis in parenchymal tissues or the tumor microenvironment; disrupt normal metabolic processes; and undermine tissue integrity." (PMID 31214171, 2019). "Combining monoclonal CD38 antibodies with CAR-T and BiTE therapies may eradicate MM tumor cells more precisely and effectively." (PMID 31779273, 2019). "Both in vitro T cell cytotoxicity assays, as well as in vivo combination treatment regimens, suggest that the upregulation of CD38 leads to an immunosuppressed TME and targeting CD38 together with the blockade of the PD-1 axis leads to improved anti-tumor immune responses." (PMID 31878283, 2019). "While providing evidence to support the use of anti-CD38 therapy in these solid tumor models, the expression of CD38 on other immune populations or even the tumor cells themselves was not analyzed in these studies." (PMID 31878283, 2019). "Finally, we provide a summary of therapeutic approaches to CD38 inhibition and ‘NAD+ boosting’ for treatment of metabolic dysfunction observed during aging and in tumor immunity." (PMID 31214171, 2019). "As this study was completed in nude mice, this reduction in tumor growth is likely due to CD38 on tumor cells and does not account for the impact of CD38-expressing immune cells in promoting tumor growth." (PMID 31878283, 2019).
tumor (continued). "The researches completed in solid tumors are largely supportive of each other, in that regardless of the cell type expressing CD38, the effect is immunosuppressive and tumor-promoting." (PMID 31878283, 2019). "The therapeutic benefit of these antibodies is thought to be mediated by their cytotoxic effects on tumor cells rather than by antagonizing the enzymatic activity of CD38." (PMID 29636685, 2018). "Isatuximab (formerly known as SAR650984) is a humanized anti-CD38 mAb that exerts a strong pro-apoptotic activity independent of cross-linking agents, and potent anti-tumor activity related to CDC, ADCC and ADCP." (PMID 30546360, 2018). "ADO is produced from the dismantling of mono- and dinucleotides (ATP and NAD+) and their byproducts (ADP, ADPR, AMP) by a set of ectoenzymes (CD39, CD38, CD203a, and CD73), of interest to both basic and clinical research because of their involvement in tumor biology and immune response." (PMID 29731713, 2018). "Additionally, alternative surface tumor antigens such as CD20, CD30, CD33, CD123, CD38, CD138, Ig κ light chain and Lewis-Y are accompanied with off-target binding." (PMID 29448937, 2018). "The production of extracellular adenosine is mediated by the cell surface ectoenzymes CD73, CD39, and CD38 and therapeutic agents have been developed to target these as well as the downstream adenosine receptors (A1R, A2AR, A2BR, A3R) to enhance anti-tumor immune responses." (PMID 30513816, 2018). "In ongoing clinic trials, the surface tumor antigens CD20, CD30, CD33, CD123, CD38, CD138, Ig κ light chain and Lewis-Y, have been applied as CAR targets, providing a pool of target antigen candidates in cancer treatment, although their clinical outcome remains further determined." (PMID 29448937, 2018). "ATRA may be administered in combination with CD38-specific CAR T cells to up-regulate CD38 expression on malignant cells and consequently to improve CAR T cell-mediated anti-tumor activity." (PMID 30546360, 2018). "These tumor-specific T-cells were generated using splenocytes of GREAT mice and were co-transferred into tumor-bearing mice that received infusion of different stem and progenitor cell populations (Sca1+HSCs, cKit+HSCs, CD133+HSCs, CD38+HSCs, or CCR2+HSCs)." (PMID 30333482, 2018). "The results show that K-rhein significantly attenuated primary B16F10 tumor outgrowth in WT, but not in Cd38‒/‒ mice, indicating that the K-rhein inhibitory effect was CD38-dependent." (PMID 30159123, 2018). "Moreover, intracellular production of ADPR by CD38 was reported in NK cells and shown to modulate Ca2+ signalling by gating TRPM2 channels and contributing to the anti-tumor activity of NK cells." (PMID 29463868, 2018). "The tumour cells were positive for B-lineage markers including Oct-2 and Bob-1 as well as ALK in all cases, while a large proportion of cases were positive for plasma cell markers including CD38, CD138, MUM1 and VS38C (more than 75%)." (PMID 28665943, 2017). "If CD38 is a major driver in a particular ALL patient, then it may be more likely miR-708-5p is a tumor suppressor in that cancer." (PMID 29050362, 2017). "CD38 and CD123 may also be two important targets for refractory/relapsed ALL, as the former could reduce on-target off-tumor effects and the latter shows a strong anti-tumor effect on CD19-negative ALL mice in preclinical trials." (PMID 28413717, 2017). "Tumor cells were strongly positive with EMA, HHV8, LMP1, CD38, CD138, and kappa light chains." (PMID 28280640, 2017). "Despite these, the potential role of CD38 in neoplastic transformation and tumor progression remains elusive, as no direct regulatory mechanisms have been elucidated." (PMID 27391070, 2016). "Similar to the findings observed with CD38 and TRPM2 in NK cells, perforin was scattered inside the NK cells mostly inside cytolytic granules and co-localizing with TRPM2 even before stimulation with tumor cells." (PMID 25879940, 2015).
tumor (continued). "Tumor cells, on immunohistochemical staining, expressed positivity for mature B cell markers CD-20, CD-19, CD-10, CD-23, CD-45, and CD-38 but were negative for CD-5,11c." (PMID 26380128, 2015). "Similar to TRPM2−/− NK cells, Cd38−/− NK cells displayed the tumor-induced initial rise in [Ca2+]i, but failed to maintain the elevated levels (36.1% of AUC of Ca2+ trace in Cd38+/+ NK cells)." (PMID 25879940, 2015). "The lack of either CD38 or TRPM2 results in a significant increase of tumor formation and reduced survival rates." (PMID 25879940, 2015). "Thus, CD38 and TRPM2 cooperate to generate the sustained Ca2+ signal and directed migration of cytolytic granules to the immunological synapse in response to tumor stimulation." (PMID 25879940, 2015). "Our results indicate that CD38 is not merely an innocent marker, but that it plays a more direct role in tumor pathogenesis and likely clinical outcomes." (PMID 26393653, 2015). "This suggests that tumor cell-induced production of ADPR, which is necessary for the cytolytic activity of NK cells, depends on the initial transient Ca2+ influx, followed by sustained Ca2+ concentration achieved by CD38 signaling." (PMID 25879940, 2015). "However, plasmacytic markers, including CD138, CD38 and EMA, are characteristically expressed, which demonstrates the terminally differentiated B-lineage origin of the tumor cells." (PMID 25009592, 2014). "Due to the significant change in the CD38+ CD4+ subset in contrast to CD8+ cells, it was further of interest to analyze whether the former would have a tumor migrating capability." (PMID 24213326, 2012). "In this study, we characterized the MDSCs of ESCC with CD38 and CD33, verified that AZD4547 could inhibit the recruitment of MDSCs through the CXCL8–CXCR2 axis in tumor tissues of hu-HSC-NOG-EXL mice, and verified the tumor suppressive effect of AZD4547 combined immunotherapy in ESCC." (PMID 40722739, 2025). "Syngeneic tumor models, which varied in their intrinsic sensitivity to murine IFNα stimulation but lacked human or murine CD38 surface expression, were treated with mCD38-mAtt to interrogate the immune-directed activity of a CD38-targeted AttenukineTM in isolation." (PMID 40315226, 2025). "The expression of CD38 by cancer cells may mediate an immune-suppressive effect by producing Extracellular Adenosine (ADO) acting through G-protein-coupled cell surface receptors on cellular components and tumor cells." (PMID 39805878, 2025). "In fact, selection of CD38+/CD138+ cells from MM patients enriches for a highly malignant population, while cell surface-shedding of the proteoglycan and accumulation of Syndecan-1/CD138 fragments in the bone-marrow tumour milieu and in circulation sets up a detrimental chemoresistance loop." (PMID 39980017, 2025). "Although anti-CD38-IFNα(att) provided potent anti-tumor activity in various MM cell lines and in human xenograft MM tumor models, it is not addressed whether it induces T cell/immune cell activation." (PMID 40243928, 2025). "Taken together, these data indicate that a CD38-directed AttenukineTM may deliver robust anti-tumor activity by leveraging both tumor- and immune-directed effects of attenuated IFNα, without eliciting systemic IFNα-related toxicities." (PMID 40315226, 2025). "Additionally, isatuximab inhibits the ADP-ribosyl cyclase activity of CD38, likely through allosteric antagonism, activates natural killer (NK) cells even in the absence of CD38+ tumor cells, and suppresses CD38+ regulatory T cells." (PMID 40005960, 2025). "All in, PRMT5 interacts with CD38 activating the phosphorylation of GSK3β through the ADO-cAMP-PKA axis, augmenting stabilization of PD-L1 expression and subsequently inhibiting CD8+ T cell-mediated tumor cell killing, supporting tumor cells to evade immune surveillance." (PMID 40701777, 2025). "However, CD38 blockade does not augment the anti-tumor efficacy of PD-L1 blockade in an immunocompetent mouse model of SCLC." (PMID 38533509, 2024).